ALB (albumin)
Diseases named in the same sentence as ALB in open-access papers (continued):
Sharing a sentence is not in itself a finding about the gene and the disease.
anemia (807 papers, 1998 to 2026). A reduction in the number of red blood cells, the amount of hemoglobin, and/or the volume of packed red blood cells. "Low albumin was associated with older age, advanced Rai/Binet stage, anemia, higher lymphocyte counts, and greater treatment requirement (all p < 0.05)." (PMID 41682996, 2026). "We found that advanced ages, high APACHE II scores, and low serum albumin levels are strongly associated with anemia, which are also associated with poor prognosis in critical ill patients." (PMID 41550749, 2026). "In group 2, anemia and urinary albumin-to-creatinine ratio were positively associated with DR, whereas eGFR was negatively associated with DR (all p < 0.05)." (PMID 42087387, 2026). "Although low vitamin D levels, low albumin levels, and iron-deficiency anemia represent red flags for aggressive disease course, supplementation did not modify the clinical course of the disease." (PMID 40364233, 2025). "ISS integrates albumin and β2-microglobulin as surrogates of disease burden and prognosis; higher stages often coincide with more severe anemia, electrolyte disturbances, and renal impairment, all linked to cardiovascular stress and events." (PMID 41143190, 2025). "•Six key risk factors were identified: age, ISS stage, ECOG score, anemia, neutropenia, and albumin." (PMID 41232431, 2025). "Age, ISS stage, ECOG score, anemia, granulocytopenia, and albumin level significantly influence pulmonary infection risk during MM chemotherapy." (PMID 41232431, 2025). "Multivariate analysis showed that age, International Staging System (ISS) stage, Eastern Cooperative Oncology Group (ECOG) score, anemia, granulocytopenia, and albumin level were significant risk factors (p < 0.05)." (PMID 41232431, 2025). "Postoperative complications occurred in 16.9%, mainly linked to poor nutritional and hematologic status (low albumin, anemia, high blood loss)." (PMID 40862782, 2025). "While both anemic and non-anemic groups showed signs of elevated nutritional risk, anemic patients exhibited significantly lower GNRI scores and albumin concentrations, highlighting a stronger association between nutritional risk and anemia." (PMID 40836330, 2025). "Our results indicate that nutritional risk, particularly reduced protein status as indicated by serum albumin levels, is associated with anemia in hospitalized geriatric patients." (PMID 40836330, 2025). "Factors significantly associated with severe anaemia included female sex, albumin levels, and creatinine levels." (PMID 39901231, 2025). "Lower prealbumin levels (aOR = 1.55) and serum albumin (aOR = 1.57) were independently associated with anemia." (PMID 41458907, 2025). "Higher albumin levels were associated with a 5% decrease in the odds of anemia (OR = 0.95, 95% CI: 0.91-0.99, P = 0.019)." (PMID 40063574, 2025). "COPD patients also frequently exhibit nutritional deficiencies (particularly albumin, iron, vitamin B12, and folate), further predisposing to anemia." (PMID 41179861, 2025). "Higher albumin levels were associated with a 4% decrease in the odds of anemia (OR = 0.96, 95% CI: 0.92-0.99, P = 0.036)." (PMID 40063574, 2025). "Pre-perforation (P = 0.014), pre-cholangitis (P = 0.042), anemia (P = 0.026), and serum albumin (P = 0.033) were associated with post-cholangitis." (PMID 41230442, 2025). "Lower albumin levels were also associated with an increased risk of severe anaemia (OR = 0.95, 95% CI: 0.91–0.99, p = 0.024)." (PMID 39901231, 2025). "Among females, anemia was linked to lower waist circumference, lower albumin levels, NNRTI regimens, microcytosis, and blood pressure but not males." (PMID 40063574, 2025). "Lower albumin levels continued to show a significant association with severe anaemia (AOR = 0.93, 95% CI: 0.88–0.98, p = 0.014), while creatinine gained significance after adjusting for other variables (AOR = 1.01, 95% CI: 1.00–1.03, p = 0.031)." (PMID 39901231, 2025).
anemia (continued). "Multivariate logistic regression analysis indicated that age, ISS stage, ECOG score, anemia, neutropenia, and albumin levels were risk factors for pulmonary infections during chemotherapy in MM patients (p < 0.05)." (PMID 41232431, 2025). "Early identification of high-risk patients, particularly those with low serum albumin, anemia, and those undergoing emergency surgeries, facilitates the implementation of tailored perioperative interventions." (PMID 39748882, 2025). "Albumin was associated with most diseases (n = 15), positively linking to a higher incidence of ulcerative colitis, certain types of anaemias and CKD." (PMID 40973818, 2025). "Higher albumin levels were linked to a 4% decrease in the odds of anemia (OR = 0.96, 95% CI: 0.92-0.99, P = 0.047)." (PMID 40063574, 2025). "Digital platforms should be programmed to flag vitamin B12 deficiency (<200 pg/mL), iron deficiency anemia (ferritin < 30 ng/mL or hemoglobin < 11 g/dL), vitamin D3 deficiency (25OHD3 < 20 ng/mL), and undernutrition (albumin < 3.5 g/dL)." (PMID 40806127, 2025). "Our study found that lower ALB levels were significantly associated with higher prevalence of anemia in cancer survivors (OR: 0.85, 95% CI: 0.80 - 0.90)." (PMID 40018412, 2025). "Factors such as female sex and creatinine levels, and decreased albumin levels emerged as significant factors associated with severe anaemia, highlighting the multifactorial nature of this complication." (PMID 39901231, 2025). "Another simplified tool, incorporating serum albumin levels, 5 min gait speed, and the presence of anemia, was also shown to be associated with adverse clinical outcomes." (PMID 39064209, 2024). "TB can cause many laboratory abnormalities such as anemia, increased erythrocyte sedimentation rate, low serum albumin level, hyponatremia, abnormal liver function, leukocytosis, and hypocalcemia." (PMID 38886797, 2024). "We further conducted causal mediation analysis to investigate the potential mediating effects of serum ferritin, albumin, and hsCRP on the associations between trace metals and anemia." (PMID 39408389, 2024). "Disruptions in hemoglobin and albumin homeostasis are known risk factors for HT, where anemia and high levels of glycated blood albumin concentrations correlate with an increased risk of HT." (PMID 38893680, 2024). "Significantly higher rates of anemia and deficiencies in calcium, vitamin D, vitamin B12, and albumin were recorded in the rOAGB at 2 years FU compared to pre-operatively." (PMID 38231451, 2024). "In patients aged 30 to 59 years with these symptoms certain blood test abnormalities strongly predict risk of any undiagnosed cancer; these include anaemia, low albumin, raised platelets, abnormal ferritin, and raised inflammatory markers." (PMID 39078806, 2024). "Our study similarly observed relationships between low albumin levels and higher hsCRP levels with an increased risk of anemia, further supporting the significant role of inflammation in anemia development." (PMID 39408389, 2024). "In this study, we found that serum ferritin, albumin, and hsCRP were involved in the association between Ni, Co, and Se and anemia, accounting for the proportions ranging from 10.29% to 58.18% when using mediation analysis." (PMID 39408389, 2024). "The ln-transformed serum ferritin and albumin levels were associated with a decreased risk of anemia, with ORs of 0.94 (95%CI: 0.92, 0.96) and 0.98 (95%CI: 0.98, 0.99), respectively." (PMID 39408389, 2024). "Invisible blood loss after PLIF often leads to patients with a low nutritional status (albumin < 35 g/L), causing anemia or aggravation of anemia." (PMID 37480018, 2023). "Anaemia associated with chronic disease, higher urea levels and lower albumin levels were more common in patients with symptoms of RLS." (PMID 38357105, 2023).
anemia (continued). "Sleep disturbances, peripheral sensory loss, chronic disease-related anaemia, increased urea and decreased albumin levels were more common among patients with RLS symptoms." (PMID 38357105, 2023). "In this study, we investigated the association between LRG1 and several iron deficiency anemia markers, including hemoglobin (Hb), albumin, red cell distribution width (RDW), iron, ferritin, and Hb transferrin saturation." (PMID 37513518, 2023). "In the present study, we demonstrated that rats subcutaneously transplanted with SLC cells displayed weight loss, muscle atrophy, severe anorexia, anemia, elevated inflammatory marker levels, and decreased serum albumin levels." (PMID 37893197, 2023). "A cohort study in West Africa that investigated the nutritional status of HIV patients who received HAART for 1 year reported that low albumin was associated with anemia." (PMID 37575113, 2023). "In critically ill patients, hypomagnesemia is common and significantly associated with older age, lower albumin, potassium, calcium and phosphate, and anemia." (PMID 37400755, 2023). "The incidence of insomnia, fatigue, weight loss, anemia, dry mouth, and serum albumin was significantly lower in the CBT group than in the TAU group." (PMID 37350940, 2023). "The first PDP plot shows the association between a selected nutrition related parameter (albumin) and an anemia related parameter (HCT)." (PMID 36403633, 2023). "The high-risk group had lower HGB, HCT, ALT, ALB levels, and anemia and hypoproteinemia were more severe in this group than in the other two groups." (PMID 37559927, 2023). "A similar significant association was also found between anaemia and serum albumin (χ2= 26.614, p < 0.001) and long duration of comorbidities (χ2= 13.955, p = 0.001)." (PMID 38957852, 2023). "The recent study suggests that those with an increasing number of positive markers of frailty (eg, the 5-m walk test, anemia, and low albumin level) are at an increased risk of mortality after TAVR." (PMID 36590743, 2022). "Our previous study suggested that baseline anemia and serum albumin were independent risk factors for incident ESRD in DN patients." (PMID 36079889, 2022). "In this study, we took care to adjust the models for confounding factors such as inflammation, anemia, and serum albumin, and demonstrated that low iron was associated with PD-related peritonitis." (PMID 35458175, 2022). "The associations of higher body mass index, anemia, higher C-reactive protein and lower plasma albumin with longer time required for performance of the 9-hole peg test suggest that overall health seems to be a major determinant of hand dexterity." (PMID 36171358, 2022). "The nutritional status of the patients were usually poor after obstruction, and there were weight loss, anemia, albumin, cholinesterase reduction, low iron and calcium." (PMID 35568851, 2022). "In HD patients, white skin, older age, low serum albumin levels, low and elevated serum phosphorus levels and anaemia have all been identified as risk factors for mortality over the first year of HD initiation." (PMID 34640538, 2021). "Raised CRP, anaemia and low albumin were biochemical factors associated with all-cause mortality; with anaemia and low albumin also being associated with commencing systemic therapy." (PMID 33579772, 2021). "The PG-SGA related factors were patients' age (p = 0.013), BMI (p = 0.001), weight loss (p = 0.001), anemia (p = 0.005), pre-albumin (p = 0.010), albumin (p = 0.002), tumor location (p = 0.001), tumor size (p = 0.002), and NIH classification (p = 0.001)." (PMID 34778339, 2021). "Simultaneous achievement of dialysis dosage, anemia, and serum albumin targets was associated with a marked reduction in mortality and other studies extend these observations to include serum calcium, phosphorus, and PTH targets." (PMID 34620096, 2021).
anemia (continued). "Multivariable analyses continued to confirm that age, pack years, N-stage, lymph node ratio (LNR), anemia and albumin were independent risk factors for OS." (PMID 32744320, 2020). "Factors positively associated with the increase in albumin levels were low baseline albumin levels and anemia in the present study." (PMID 33370299, 2020). "The multivariable logistic regression analysis performed here revealed that albumin was independently associated with recovery from anemia." (PMID 33072136, 2020). "Prior RT history (p = 0.007), free flap reconstruction for pharyngeal defect (p < 0.001), postoperative lower serum albumin level (p = 0.025), and postoperative anemia (p = 0.04) were all significantly associated with higher probability of prolonged LOS." (PMID 32673371, 2020). "His serum iron (SI) (7.45 mmol/L) and ferritin (1.1 ng/ml) were low, suggesting iron deficiency anemia, and his 25-hydroxy vitamin D (4.89 ng/ml), albumin (ALB) (30 g/L) were also low." (PMID 33190630, 2020). "Based on univariate analysis in the training set, we appraised eight parameters, including age, pack years, N-stage, number of positive of lymph node (PLNs), lymph node ratio (LNR), TNM stage, anemia and albumin, were associated with OS probability." (PMID 32744320, 2020). "In our study of three independent cohorts of adults with SCD, serum albumin concentration was significantly associated with severity of anemia, as well as liver and renal dysfunction." (PMID 32776978, 2020). "Recovery from anemia was associated with increased pre-ATT albumin levels whereas persistent anemia was related to higher total protein levels in serum." (PMID 33072136, 2020). "The cause of fatigue experienced by this subset of PLM patients is likely to be multifactorial and associated with prevalent complications such as anemia and low albumin levels, psychosocial factors including depression and anxiety, and insomnia." (PMID 32673242, 2020). "Higher IL-34 level was also associated with poorer general condition, such as anemia and low serum albumin level, leading to more severe cardiac dysfunction." (PMID 30050466, 2018). "Some of these aligned with the”integrated albunemia” model of aging proposed recently, which implicated anemia, inflammation and low levels of albumin and calcium as markers of mortality and frailty." (PMID 28422991, 2017). "Development of SSI was associated with low serum albumin, anaemia, type of suture used, and dirty wound class." (PMID 28168215, 2017). "Anemia due to a chronic disease in dolphins has been associated with a decrease in albumin and an increase in bilirubin." (PMID 29190288, 2017). "For instance, serum albumin levels are significantly lower during active VL infections than those in healthy control subjects, as are Ht levels, and both anemia and low albumin levels were found to be risk factors for poor clinical outcomes in VL." (PMID 26787691, 2016). "Edema, fatigue, hair loss, erythema, mild anemia, decreased albumin concentrations, and headaches frequently accompany normal pregnancy." (PMID 27442513, 2016). "Most rapid progression group was associated with proteinuria, phosphorus, albumin, and anemia in the follow-up as well as baseline eGFR and male, and other factors were all negated." (PMID 26100399, 2016). "Among patients treated with BOC, female gender, higher BMI, higher CCI, lower baseline albumin, and lower Hb count were associated with development of severe anemia." (PMID 27356107, 2016). "Recurrent episodes of peritonitis, with negative culture, spontaneously regressed, in association with anemia, low albumin and high C-reactive protein, can be found in case of EPS." (PMID 27964725, 2016). "In conclusion, the results of this study indicate that hemodialysis patients with low serum albumin are at greater risk of anemia." (PMID 26644884, 2015).
anemia (continued). "AKI was associated with a reduced LVEF, diuretic use, anemia, heart valve surgery, duration of extracorporeal circulation, hemodynamic instability and the use of albumin, pentastarch 10% and transfusions." (PMID 25394836, 2014). "Age, anemia, leukopenia, thrombocytopenia, serum albumin levels, and β2-microglobulin values were linked to survival." (PMID 24995279, 2014). "The study also described the clinical impact of infection and documented that an acute phase with anorexia, transient weight loss and anaemia, lowered lymphocyte, eosinophil count and serum-albumin takes place." (PMID 23289937, 2013). "Haemoglobin concentrations are inversely related with glycated albumin and hyperglycaemia is possibly associated with decreased erythrocytes lifespan, indicating a likely contribution of glucose control to anaemia." (PMID 22876293, 2012). "NSCLC patients had a higher incidence of anemia, especially the incidence of chemotherapy-related anemia, age, clinical stage, PS score, albumin levels were the risk factors of pre-treatment cancer-related anemia." (PMID 20959070, 2010). "Early identification of risk factors, such as low serum albumin, anemia, and emergency surgeries, enables personalized perioperative management strategies, including nutritional optimization and careful intraoperative monitoring, which can significantly reduce the risk of WD." (PMID 39748882, 2025). "Interestingly, albumin levels also showed reciprocal causal associations with genetic liability to the risk of ulcerative colitis, certain types of anaemias and CKD." (PMID 40973818, 2025). "Univariate COX analysis showed lower KPS score, higher LabBM score, pretreatment metastasis, failure to achieve CR or PR after treatment, higher T stage, N+, higher TNM stage, lower serum albumin level, and pretreatment anemia were associated with poorer OS (P < .05)." (PMID 40958277, 2025). "We also found that low Albumin is associated with severe anaemia in PLWH." (PMID 39901231, 2025). "Additionally, low albumin levels, associated with anemia in people living with HIV, also reflect poor nutritional status and increased catabolism." (PMID 40063574, 2025). "Additionally, lower levels of albumin at the time of diagnosis are linked to the severity of anemia." (PMID 40165528, 2025). "Furthermore, albumin mediated the associations between Ni, Co, and Se and anemia, accounting for 15.83%, 20.75%, and 23.26% of the effects, respectively (all p for mediation < 0.05)." (PMID 39408389, 2024). "Important risk factors included neurological diseases (46.02%), spinal cord injuries (14.7%), and nutritional deficiencies, as indicated by anemia (10.43g/dL; 95% CI [10.04; 10.82]), low serum albumin (2.56 g/dL; 95% CI [2.43; 2.69]) and proteins (5.54 g/dL; 95% CI [5.34; 5.73])." (PMID 39766011, 2024). "We found that patients with longer operation time, lower preoperative hemoglobin, ASA Physical Status > 2, total hip arthroplasty, anemia, autotransfusion, lower preoperative fibrinogen, and lower preoperative albumin were significantly associated with increased transfusion risk." (PMID 38840126, 2024). "Based on our analysis, the late RISS, ISS staging, high-risk genetic status, anemia, high serum globulin level, and low albumin levels were strongly associated with shorter PFS, which corroborates with published clinical trials and findings within clinical practice." (PMID 37370013, 2023). "Previous studies have reported low albumin levels and anemia as risk factors for falls in patients hospitalized in the acute phase, and these could be equally applied to patients with acute stroke." (PMID 37915000, 2023). "Multivariable logistic regression analysis using variables with significant differences for males identified loop diuretics, aspirin, L-type CCBs, alpha–beta blockers, alpha blockers, anemia, and a low albumin level as independent factors that increased the risk of SRD." (PMID 37754834, 2023).